CASR (calcium sensing receptor)
Diseases named in the same sentence as CASR in open-access papers (continued):
Sharing a sentence is not in itself a finding about the gene and the disease.
colitis (continued). "Therefore, a major finding of our study is—contrary to our initial hypothesis that CaSR inhibition might be more effective in medium-grade colitis—that the effectiveness of CaSR inhibition as an anti-inflammatory measure seems to be proportional to disease severity." (PMID 39770982, 2024). "Whether these effects are connected to a possible pro-inflammatory role of the CaSR in the intestine is still under debate and necessitates clarification, in particular in light of the possible detrimental effects that a calcimimetic-based therapy could exert in patients suffering from colitis." (PMID 36467702, 2022). "We treated female Balb/C mice with dietary calcium and protein (nutritional agonists of the CaSR) or pharmacological CaSR modulators (the agonists cinacalcet and GSK3004774, and the antagonist NPS-2143; 10 mg/kg), then induced colitis with DSS." (PMID 31888253, 2019). "Second, we used highly selective pharmacological CaSR ligands to target the luminal CaSR in the intestines and hypothesized that modulating the CaSR will influence DSS-induced colitis in mice." (PMID 31888253, 2019). "Moreover, our data show for the first time that orally administered positive allosteric modulators of the CaSR do not alleviate clinical symptoms of colitis." (PMID 31888253, 2019). "We showed previously that CaSR inhibition with NPS 2143, a negative allosteric modulator of the CaSR, somewhat ameliorated the symptoms of chemically induced severe colitis in mice." (PMID 39770982, 2024).
epilepsy (9 papers, 2010 to 2025). "The activation of calcium-sensing receptor (CaSR) has been linked to neuron damage in epilepsy and has attracted research interest recently." (PMID 36093409, 2022). "Gene mutation of CaSR can change the abundance of receptors in the plasma membrane, strengthen the activation of related signaling pathways, and alter the regulation of the central nervous system to induce epilepsy." (PMID 36093409, 2022). "Clearly additional study is required to determine how CaSR mutations lead to epilepsy." (PMID 20052292, 2010). "However, subjects harboring this mutation unexpectedly displayed levels of serum calcium, phosphate, sodium, potassium, and parathyroid hormone within reference range, suggesting that the effect of the CaSR for epilepsy phenotypes is allele and tissue-specific." (PMID 31336912, 2019). "However, the CaSR−/− mutation increases release probability at excitatory synapses at basal [Ca2+]o which is expected to increase neuronal excitability and increase the risk of epilepsy." (PMID 20052292, 2010). "GAA treatment significantly reduced the cortical neuron apoptosis of epilepsy and the expression of calcium-sensing receptor, p-P38, p-JNK, cleaved caspase-3, and Bax but increased the expression of both p-ERK and Bcl-2." (PMID 36093409, 2022). "The expression level of CaSR in hippocampus tissue was increased in the epilepsy group compared to the control group (p < 0.05), but its expression was decreased in both the sodium valproate group and GAA group compared with the epilepsy group (p < 0.05)." (PMID 36093409, 2022). "Also, there is a positive link between CaSR and the mitogen-activated protein kinase (MAPK) pathway; for example, the overexpression of CaSR can cause epilepsy by affecting the expression of proteins linked to the MAPK pathway." (PMID 36093409, 2022). "Our results showed that protein expression of p-JNK and p-p38 in the hippocampus tissue of epileptic rats increased significantly, and there was a significant increase in CaSR expression in the epilepsy group compared with the control group, while the expression of p-ERK was decreased." (PMID 36093409, 2022). "An important goal for the field is to determine the relative contributions of these signaling pathways to neuronal function to facilitate our understanding behind the role of CaSR signaling in pathogenesis of acute neurological diseases like stroke, traumatic brain injury, and epilepsy." (PMID 27065884, 2016). "In parallel, CaSR levels have been found to be increased in animal models following induction of seizures as well as traumatic brain injury hinting at a potential role for CaSR in the development of epilepsy following status epilepticus or traumatic brain injury." (PMID 27065884, 2016). "CaSR is associated with epilepsy and dementia however the consequences of CaSR activation in the CNS have not been fully characterized." (PMID 20052292, 2010). "Modulators of calcium-sensing receptors (CaSR) could, in principle, recalibrate neuronal sensitivity to [Ca2+]o fluctuations, while interventions that stabilize astrocytic Ca2+ buffering might reduce excitability in epilepsy or normalize synaptic signaling in AD." (PMID 41227353, 2025). "The aim is to test antiepileptic effect of GAA and provide a theoretical target of GAA on the calcium-sensing receptor and MAPK pathway in order to pave the way for its use in epilepsy treatment." (PMID 36093409, 2022). "This study will summarize existing evidence to assess the effects of SPGL on CaSR and ARP in hippocampus tissue of epilepsy following dementia." (PMID 32872049, 2020). "This systematic review will first summarize current available literature to assess the effects of SPGL on CaSR and ARP in hippocampus tissue of rats with epilepsy following dementia." (PMID 32872049, 2020).
epilepsy (continued). "This study will investigate the effects of Spore Powder of Ganoderma Lucidum (SPGL) on CaSR and apoptosis-related proteins (ARP) in hippocampus tissue of epilepsy following dementia." (PMID 32872049, 2020). "While the pathophysiological mechanism of cell damage and apoptosis induced by epilepsy has not been fully elucidated, this and other studies have shown that the activation of CaSR is indeed involved in epilepsy-induced cell damage and apoptosis." (PMID 36093409, 2022). "This study will retrieve all potential studies from both electronic databases (Cochrane Library, EMBASE, MEDLINE, CINAHL, AMED, and CNKI) and other literature sources to assess the effects of SPGL on CaSR and ARP in hippocampus tissue of epilepsy following dementia." (PMID 32872049, 2020). "The findings of this study will provide evidence to help judge whether SPGL is effective on CaSR and ARP in hippocampus tissue of rats with epilepsy after dementia." (PMID 32872049, 2020). "The findings of this study may provide helpful evidence of SPGL on CaSR and ARP in hippocampus tissue of epilepsy following dementia." (PMID 32872049, 2020). "Thus, this systematic review will investigate the effects of SPGL on CaSR and ARP in hippocampus tissue of rats with epilepsy after dementia." (PMID 32872049, 2020).
cardiac hypertrophy (8 papers, 2018 to 2025). "Calhex 231 inhibits autophagy by suppressing CaMKKβ-AMPK-mTOR pathway, thereby, ameliorating cardiac hypertrophy caused by CaSR activation." (PMID 41208959, 2025). "CaSR activation has been implicated in myocardial hypertrophy, apoptosis, and I/R injury." (PMID 41208959, 2025). "The aim of the present study was to investigate the underlying mechanism of CaSR in cardiac hypertrophy and apoptosis and to evaluate whether the protective effect of AsIV against myocardial injury is associated with CaSR and its related signaling pathway." (PMID 30364197, 2018). "During myocardial hypertrophy, CaSR mediated autophagy is increased, whereby, elevated Ca2+ triggers several Ca2+-dependent signaling pathways, culminating into cardiac hypertrophy." (PMID 41208959, 2025). "In the present study, we found that as blood pressure increased and CaSR levels decreased, myocardial hypertrophy and fibrosis increased in SHRs, ultimately exacerbating detrimental cardiac remodeling." (PMID 38715976, 2024). "This study provided convincing evidence that R568, a positive regulator of CaSR, was effective in lowering blood pressure in spontaneously hypertensive rats (SHRs), improving cardiac function by alleviating cardiac hypertrophy and fibrosis." (PMID 38715976, 2024). "CaSR inhibition effectively reduces autophagy by inhibitingCaMKKβ (eCa2+/calmodulin-dependent protein kinase kinaseβ),thus ameliorating cardiac hypertrophy." (PMID 39484135, 2024). "Although the regulation of the CaSR on CaMK-II in cardiac hypertrophy and apoptosis has been investigated, the role of this special isotype, CaMK-IIδ, in CaSR-regulated cardiac inflammation still needs to be identified." (PMID 36231037, 2022). "The CaSR plays an important role in mediating pathological myocardial hypertrophy and in cardiovascular diseases such as myocardial ischemia-reperfusion injury, heart failure, and vascular calcification." (PMID 34690749, 2021). "In summary, combined with our previous research, these results strongly demonstrate that SF can inhibit cardiac hypertrophy in rats through regulating the CaSR-mediated signal pathway and inhibiting the PKC-MAPK signaling pathways." (PMID 34690749, 2021). "This provide more sufficient evidence to prove that SF influence on cardiac hypertrophy via CaSR singnaling pathway." (PMID 34690749, 2021). "The results suggested that CaSR-mediated changes in [Ca2+]i and CaMKII and CaN signaling pathways contribute to cardiac hypertrophy and apoptosis and are involved in the protective effect of astragaloside IV against cardiac injury." (PMID 30364197, 2018). "What is more, AsIV suppressed CaSR activation, downregulated Ca2+/CaMKII/CaN signaling pathways, and subsequently attenuated cardiac hypertrophy and apoptosis induced by Iso." (PMID 30364197, 2018). "The present study demonstrated, for the first time, that CaSR contributes to cardiac hypertrophy and apoptosis by increasing [Ca2+]i and activating Ca2+-dependent CaMKII and CaN pathways." (PMID 30364197, 2018). "The results demonstrated that CaSR activation contributed to cardiac hypertrophy and apoptosis, and the effect of CaSR was mediated by the activation of Ca2+-dependent CaMKII and CaN signaling pathways." (PMID 30364197, 2018). "The results showed that activation of CaSR with GdCl3 (30 μM) induced cardiac hypertrophy, as indicated by the increased cell surface area and increased mRNA expression of ANP and BNP in H9C2 cells, effects that were similar to the effects of Iso (10 μM)." (PMID 30364197, 2018). "AsIV also attenuated GdCl3-induced cardiac hypertrophy and apoptosis through the downregulation of CaSR expression and [Ca2+]i." (PMID 30364197, 2018). "Pretreatment with AsIV attenuated cardiac hypertrophy and apoptosis, improved cardiac function, and downregulated CaSR expression while also improving mitochondrial structure and MMP and inhibiting cytochrome c release from the mitochondria." (PMID 30364197, 2018).
cardiac hypertrophy (continued). "It has been previously reported that CaSR activation with GdCl3 can induce cardiac hypertrophy and apoptosis." (PMID 30364197, 2018). "In the present study, we investigated the role of CaSR activation in cardiac hypertrophy and apoptosis and the relationship between CaSR and Ca2+-dependent CaMKII and CaN signaling pathways both in vivo and in vitro." (PMID 30364197, 2018). "The present study showed that 100 μM AsIV inhibited Iso-induced cardiac hypertrophy similarly to the CaSR antagonist NPS2143 (1 μM)." (PMID 30364197, 2018). "In neonatal rat ventricular myocytes and transverse aortic constriction mice, the hypoxia-induced development of cardiac hypertrophy could be prevented by inhibiting the CaSR with Calhex231." (PMID 36231037, 2022). "In the following sections, we discuss the CaSR-mediated intracellular communication in several classical cardiovascular diseases, including ischemia/reperfusion damage, myocardial hypertrophy, diabetic cardiomyopathy, and cardiorenal syndrome, which is associated with the heart–kidney interaction." (PMID 36231037, 2022). "The overexpression of CaSR contributes to the development of cardiac hypertrophy." (PMID 34690749, 2021). "Furthermore, the effects of CaSR activation on cardiac hypertrophy, apoptosis and the CaMKII and CaN pathways were enhanced by Iso administration." (PMID 30364197, 2018). "Activation of CaSR has been reported to be involved in the development of various cardiovascular diseases including cardiac hypertrophy and apoptosis, but the molecular mechanism of the involvement of CaSR activation in heart failure has not yet been clarified and thus needs to be further explored." (PMID 30364197, 2018). "As an agonist of CaSR, GdCl3 gets involved in cardiac hypertrophy and apoptosis by activating CaSR." (PMID 30364197, 2018). "Furthermore, previous studies suggested that the regulation of the CaSR could target the mitochondria and ER during cardiac hypertrophy." (PMID 36231037, 2022). "Consistent with the results of previous studies, the present study demonstrated that CaSR contributed to cardiac hypertrophy and apoptosis induced by Iso but that the mechanism may be related to mitochondrial dysfunction and Ca2+-dependent CaMKII and CaN pathways." (PMID 30364197, 2018). "Upon review of the previous studies, it was found that CaSR contributes to cardiac hypertrophy induced by angiotensin II, Iso, and transverse aortic constriction, and the mechanism may involve [Ca2+]i, the sarcoplasmic reticulum (ER), the mitochondrial death pathway and autophagy." (PMID 30364197, 2018). "Therefore, CaSR may be a promising therapeutic target for the treatment of myocardial hypertrophy." (PMID 34690749, 2021). "Although some progress has been made in understanding the role of CaSR in the cardiovascular system, the exact mechanism by which CaSR participates in cardiac hypertrophy and the downstream signaling pathway is not fully understood." (PMID 30364197, 2018).
parathyroid hyperplasia (8 papers, 2020 to 2025). A hyperplasia that involves the parathyroid gland. "Future studies should further analyze the correlation between miR-301a-5p and CaSR/PTH levels in SHPT patients to validate its clinical significance and explore the direct role of the miR-301a-5p-CaSR axis in parathyroid hyperplasia or calcification." (PMID 40394480, 2025). "Dr. Slatopolsky and collaborators demonstrated the decreased expression of the calcium-sensing receptor in parathyroid tissue and that dietary phosphate restriction prevents both decreased calcium-sensing receptor expression and parathyroid hyperplasia in kidney failure." (PMID 39364464, 2024). "Current treatment based on activating the parathyroid calcium-sensing receptor (CaSR) using calcimimetics such as Cinacalcet, aims to decrease plasma PTH levels and inhibit the progression of parathyroid hyperplasia." (PMID 39761264, 2025). "The expression of calcium-sensing receptor (CaSR) in the PTGs directly modulates PTH secretion and probably contributes to parathyroid hyperplasia." (PMID 32517664, 2020).
Stroke (8 papers, 2016 to 2022). Sudden impairment of blood flow to a part of the brain due to occlusion or rupture of an artery to the brain. "For instance, calcium-sensing receptor (CASR) has been reported to be associated with the pathophysiology of stroke, and it can act as a target for ischemic neuroprotection." (PMID 36118760, 2022). "Moreover, in view of the present observations and the known role of platelets in the pathophysiology of cardiac infarction and stroke, CaSR activation could counteract upregulation of platelet activity by phosphate and thus reduce the risk of cardiac infarction and stroke in CKD patients." (PMID 33804889, 2021). "In regard to this topic, an upregulation of the CaSR and an intensified Aβ-os•CaSR signaling induced the death of neurons in rodent models of cerebral ischemia/hypoxia/stroke." (PMID 27199760, 2016). "CaSR-dependent reduction of VGSC sensitivity to membrane potential adds further complexity to extracellular calcium signaling and identifies another potential mechanism by which CaSR stimulation may influence neuronal death following stroke and traumatic brain injury." (PMID 33973519, 2021).
autoimmune hypoparathyroidism (7 papers, 2018 to 2025). An autoimmune form of hypoparathyroidism. "Activating calcium-sensing receptor antibodies causing autoimmune hypoparathyroidism with nivolumab was recently reported." (PMID 32587615, 2020). "Recent reports demonstrated that activating calcium-sensing receptor antibodies are associated with the development of autoimmune hypoparathyroidism in a patient receiving nivolumab." (PMID 32587615, 2020). "Autoimmune hypoparathyroidism can be caused by either immune-mediated destruction or by hyperactivation of the CaSR by activating autoantibodies." (PMID 30791949, 2019). "Isolated autoimmune hypoparathyroidism has been related to antiparathyroid and anti-CaSR antibodies, but the pathogenic role of these antibodies is still poorly characterized." (PMID 29694629, 2018). "Moreover, the CaSR has been found to be implicated in autoimmune-hypoparathyroidism, recently found also in patients treated with immune-checkpoint inhibitors." (PMID 36467702, 2022). "In the patients with AHH or autoimmune hypoparathyroidism reported by other researchers, the patient sera were found to be reactive against several peptides that can be found in the CaSR-ECD (peptides 41–69; 114–126; 171–195; 214–236; 344–358; and 374–391)." (PMID 36099030, 2022). "There have been some prior reports that the serum from patients with AHH or autoimmune hypoparathyroidism reacts to certain peptides that match segments of the CaSR-ECD." (PMID 36099030, 2022). "The prevalence of antiparathyroid and anti-CaSR antibody positivity in individuals with suspected autoimmune hypoparathyroidism is variable (between 25 to 40%), and the measurement of these antibodies is generally limited to research studies." (PMID 29694629, 2018). "For autoimmune hypoparathyroidism, APS-1 (biallelic AIRE defects) is the canonical central-tolerance failure, but agonistic anti-CaSR and anti-NALP5 antibodies explain isolated/APS-like phenotypes outside classic APS-1." (PMID 41465179, 2025).
autoimmune polyendocrine syndrome type 1 (7 papers, 2013 to 2025). Autoimmune polyendocrinopathy type 1, or APECED syndrome, is a genetic disease that manifests in childhood or early adolescence with a combination of chronic mucocutaneous candidiasis, hypoparathyroidism and autoimmune adrenal failure. "The acquired diseases are related to the presence of anti-CaSR antibodies, which can cause hyper- or especially hypocalcemia disorders (for instance in APECED syndromes), determined by their functionality." (PMID 28122587, 2017). "On the other hand, a gain-of-function effect is also observed in autoimmune polyglandular syndrome type 1, in which autoantibodies bind the N-terminus of the CaSR stabilizing activating conformation of the receptor." (PMID 24244430, 2013). "CaSR autoantibodies and CaSR-activating autoantibodies have previously been identified in patients with idiopathic hypoparathyroidism and autoimmune polyendocrine syndrome type 1 (APS1) and have also been described in a patient treated with nivolumab." (PMID 30791949, 2019).